ESR1 (estrogen receptor 1)
Diseases named in the same sentence as ESR1 in open-access papers (continued):
Sharing a sentence is not in itself a finding about the gene and the disease.
breast cancer (continued). "MSI2 has been reported to maintain protein and RNA stability to regulate ESR1 function in breast cancer." (PMID 31888685, 2019). "Expressions of estrogen receptor 1 (ESR1), progesterone receptor (PGR), and human epidermal growth factor receptor type 2 (HER2) are deficient in triple-negative breast cancer (TNBC) breast cancer." (PMID 31409331, 2019). "Another study which used a multiplex ligation-dependent probe amplification (MLPA) approach to analyze 104 invasive breast cancers identified 16% of samples harbored ESR1 amplifications consisting of low level gains." (PMID 31106278, 2019). "The results of network analysis show that RYNXC treat breast cancer by regulating the ESR1, PGR and PTGS2." (PMID 30906412, 2019). "The ESR1 gene encodes the estrogen receptor, and some studies try to use the ESR1 gene as a marker gene in breast cancer therapy." (PMID 30866472, 2019). "In this review, we summarize the pre-clinical and clinical findings defining the characteristics of ESR1 mutant breast cancer, and highlight the potential clinical developments in this field." (PMID 31795152, 2019). "BTF3 promotes the proliferation, survival, and migration of ER + breast cancer cells by modulating ESR1 expression and ERα-dependent transcription." (PMID 31138311, 2019). "Many clinically important genes in breast cancer, e.g. ESR1 and ERBB2, appear to follow a bimodal expression distribution across the samples of a cohort." (PMID 31072345, 2019). "In the TCGA BRCA data, our model identified that around 31.9% genes were best fitted by either the MG or LTMG model with more than one peaks, such as the ESR1 and PGR genes that are associated with the breast cancer subtype." (PMID 31861972, 2019). "Other than miR-106-5p and miR-17-5p, miRNAs such as miR-375, miR-592, and miR-135a also influence breast cancer proliferation by modulating ESR1, ERBB4 pathway, and miR-135a function as prognostic marker in ER-positive breast cancer." (PMID 30989460, 2019). "Mutations in the ESR1 gene (ESR1m) are important mechanisms of resistance to endocrine therapy in estrogen receptor-positive advanced breast cancer and have been recognized as a prognostic and predictive biomarker as well as a potential therapeutic target." (PMID 31511774, 2019). "For example, ESR1’s interaction with MED1 is required for ESR1-mediated gene transcription, E2/ESR1-dependent mammary progenitor/stem cell function, and breast cancer cell growth." (PMID 30538295, 2019). "miR-221/222 former potently downregulate ESR1, reflected in a shift toward the Basal breast cancer subtype." (PMID 30833639, 2019). "ESR1 is a highly correlated gene; it drives growth in the majority of human breast cancers by binding to regulatory elements and inducing transcriptional events that promote tumor growth." (PMID 31562808, 2019). "Taken together, these results demonstrate that SALL2 transcriptionally activates ESR1 via directly interacting with ESR1 promoter in breast cancer cells." (PMID 31657150, 2019). "We have previously reported that increased ESR1 gene dosage measured by qPCR has prognostic significance in breast cancer patients." (PMID 30995757, 2019). "Factor 12 also predicts insensitivity to TOP1-poisons and includes the canonical oncogenes such as ERBB2, TGFB3, ESR1 (AR), and FGFR4 that are strongly associated with breast cancer." (PMID 31695042, 2019). "It has been reported that breast cancer risk may be influenced by indirect effect of androgens via their conversion to estradiol, or by binding with AR to promote or by stopping breast cell growth, or even by binding to ESR1 and inducing proliferation in breast cells." (PMID 30975222, 2019). "This included 7 breast cancer-related genes: caspase 8 (CASP8), cadherin 1 type 1 (CDH1), estrogen receptor 1 (ESR1), ETS variant 6 (ETV6), forkhead box A1 (FOXA1), GATA-binding protein 3 (GATA3) and neurotrophic tyrosine kinase receptor type 3 (NTRK3)." (PMID 31182966, 2019).
breast cancer (continued). "More studies are required to fully understand the contribution of transcriptionally inactive in-frame and out-of-frame ESR1 fusions in breast cancer." (PMID 31106278, 2019). "This suggests that this factor represents the continuous variation in ESR1 expression in breast cancer, which is typically dichotomized to define ER+ and ER- tumors." (PMID 30379847, 2018). "We observed the expression of the ESR1 mRNA in a breast cancer cell line, MCF7 cells, transfected with the SIN3A mutant in the presence of 100 nM E2." (PMID 30375428, 2018). "WES analysis of genomic DNA extracted from tissues of breast cancers classified by ESR1 was carried out with a deep sequencer SOLiD5500." (PMID 30375428, 2018). "The etiology of endocrine therapy resistance in estrogen receptor-positive (ER+) breast cancer is complex but includes acquired somatic mutations within the ligand-binding domain (LBD) of the estrogen receptor gene (ESR1) causing ligand-independent activation." (PMID 30089255, 2018). "For example, in the case of breast cancer, elevated mRNA expression and copy number amplification of ESR1 correlate with elevated protein expression of ER, as well as with sensitivity to hormonal therapy with tamoxifen." (PMID 30053901, 2018). "From an RNA-seq screen of 81 primary, treatment-naive, ER+ breast cancers from two neoadjuvant AI clinical trials (NeoAI Trials), two PCR-validated ESR1 fusions were identified." (PMID 30089255, 2018). "One possibility is that ESR1 is responsible for the linkage between these SNPs and breast cancer or endometriosis." (PMID 30149579, 2018). "Although, ESR1 is frequently amplified in breast cancer cells, methylation-dependent silencing of this gene by CGI (CpG island) has been previously reported." (PMID 29568567, 2018). "We show here that PR binds to the ESR1 locus and is required to maintain the ESR1 gene expression in hormone-free breast cancer cells." (PMID 30301163, 2018). "There is no direct evidence that ATF6 plays a role in drug-resistance, although one study found ATF6 to be an independent predictor of increased relapse and shorter survival in primary ESR1+ breast cancers treated with tamoxifen." (PMID 30248920, 2018). "The estimated increases in the risk of BRCAX or high-risk breast cancers from the variants on FGFR2, TOX3, and ESR1 were quite similar across populations (ORs for highest compared to lowest tertile = 2.2 to 2.4)." (PMID 30323354, 2018). "In this study, we demonstrate that PR binds to the low-methylated ESR1 promoter and maintains both basal gene expression and the DNA methylation profile of the ESR1 locus in hormone-free breast cancer cells." (PMID 30301163, 2018). "The majority of ESR1 fusion transcripts have been identified in primary breast cancer, and in some of these instances patients have high-grade disease and/or resistance to endocrine therapy, implying some functionality." (PMID 30089255, 2018). "ESR1 aberrant splicing events have also been identified in circulating tumour cells from metastatic breast cancer patients that have progressed on endocrine therapy, suggesting a role in mediating resistance." (PMID 29848666, 2018). "GREB1 expression correlates with ESR1 positivity in breast cancer cell lines and primary breast tumours, and GREB1 is induced by ESR1 binding to estrogen response elements (EREs) upstream of the GREB1 promoter." (PMID 29973689, 2018). "Simultaneous suppression of AGR2 and ESR1 activity represents a potentially promising concept to be further investigated for breast cancer." (PMID 29796176, 2018). "To test this possibility, we knocked down PR in T47D breast cancer cells using the short-hairpin RNA approach (shPR) and analyzed PR and ESR1 gene expression by RT-qPCR and Western blotting assays." (PMID 30301163, 2018). "Of the four biomarkers we detected, ESR1 is the only one in common with the reported signature for luminal breast cancers (ESR1, GATA3, FOXA1, XBP1, and cMYB)." (PMID 29868123, 2018).
breast cancer (continued). "Breast cancer subtypes are most commonly classified based on the expression of the Estrogen Receptor (ESR1), Progesterone Receptor (PGR), and/or the Human Epidermal Growth Factor Receptor-2 (HER2)." (PMID 30279965, 2018). "We searched a database for the top 500 genes that are positively or negatively correlated with YBX1 and with ESR1 in breast cancer patients." (PMID 30647855, 2018). "We showed that the depletion of both PR isoforms reduces the ESR1 expression in T47D breast cancer cells; however, we cannot exclude that just one of the PR isoforms is required for the ESR1 expression." (PMID 30301163, 2018). "To determine if ZB716 is effective as an antiestrogen in a clinically relevant breast cancer model that is estrogen independent and resistant to antiestrogens, we used an ESR1 mutant cell line, T47D/Y537S that was derived from a PDX model." (PMID 29467940, 2018). "Note that bimodal genes occur in several biologically meaningful situations like fusion genes such as ERG in prostate cancer or hormone genes such as ESR1 in breast cancer." (PMID 30733688, 2018). "In vitro, XBP1s overexpression in an ESR1+ breast cancer cell line increased levels of the pro-survival protein BCL-2 and decreased mitochondrial membrane permeabilization when cells were challenged with the estrogen antagonist’s tamoxifen or fulvestrant." (PMID 30248920, 2018). "We show that PR binds to the low-methylated ESR1 promoter and maintains both gene expression and DNA methylation of the ESR1 locus in hormone-deprived breast cancer cells." (PMID 30301163, 2018). "In vitro, knockdown of GRP78 sensitizes ESR1+ breast cancer cells to paclitaxel, vinblastine, etoposide, and radiation while GRP78 overexpression confers resistance to gemcitabine." (PMID 30248920, 2018). "The breast cancer tissue containing SIN3A p.Gln944* showed a 1.6-fold higher expression level of ESR1 mRNA than breast cancer tissues containing SIN3A-WT." (PMID 30375428, 2018). "A comprehensive study of gene expression signatures in primary samples revealed an overexpression of XBP1 in luminal breast cancer, where it is co-expressed with ESR1." (PMID 30248920, 2018). "First, the ER factor is associated with both mRNA and protein expression of ESR1, AR and PR, and is enriched for gene signatures of ESR1 expression and the luminal subtype of breast cancer, which, in turn, is characterized by ESR1 overexpression." (PMID 30379847, 2018). "For example, steroid receptors like the estrogen receptor ESR1 are involved in breast cancer or the androgen receptor in prostate cancer." (PMID 29741575, 2018). "CCDC170 is only 133 kb away from estrogen receptor 1 (ESR1), and the closest SNPs to CCDC170 are associated with breast cancer and endometriosis risk." (PMID 30149579, 2018). "DNA methylation at the ESR1 promoter represents one of the main epigenetic mechanisms for stably repressing ESR1 expression in breast cancers." (PMID 30301163, 2018). "Both HDAC and mTORC1 gene expressions were higher in MDA-MB-231 TNBC cells than in luminal ESR1+MCF-7 breast cancer cells." (PMID 30050079, 2018). "Here, we report that PR binds to the low-methylated ESR1 promoter to maintain its basal expression and its low level of DNA methylation in hormone-free breast cancer cells." (PMID 30301163, 2018). "XBP1 and ESR1 are co-expressed in luminal breast cancers and in vitro work has demonstrated the existence of a feed-forward mechanism connecting the two proteins." (PMID 30248920, 2018). "The cytoplasmic localization attenuates the functions of SIN3A, leading to an increase in ESR1 expression that accelerates the cell proliferation involved in the progression of breast cancers." (PMID 30375428, 2018). "We show that inhibition of the most-enhanced binding coactivators reduced ERE-driven transcription and ESR1 mutant expressing breast cancer cell growth." (PMID 29748621, 2018).
breast cancer (continued). "In high-grade breast cancers, HDAC1 and DNA methyl transferase 3B are also recruited to the ESR1 promoter by Twist expression, causing a reduction in the ESR1 transcription level." (PMID 30375428, 2018). "Inhibition of these coactivators decreased the ability of ESR1 mutants to activate transcription and promote breast cancer growth in vitro and in vivo." (PMID 29748621, 2018). "Further analysis of the mRNA-seq data set found that GFRA1 is also strongly correlated with ESR1 mRNA in breast cancers (Spearman’s ρ = 0.52, p < 2.2e-16), suggesting that it is also a direct target of E2 signaling." (PMID 29608602, 2018). "Within the subtypes of breast cancer, one stands out as highly aggressive, coupled with a triple negative histotype for estrogen receptor α (ESR1), progesterone receptor (PR) and human epidermal growth factor 2 (HER2)." (PMID 30373175, 2018). "Anti-estrogen therapies have been used for the treatment of ESR1-positive breast cancers due to its excellent efficacy-to-toxicity ratio." (PMID 30050079, 2018). "PR-negative breast carcinoma patients present higher methylation levels of the ESR1 gene than PR-positive breast carcinomas." (PMID 30301163, 2018). "This study adds to the catalog of actionable ESR1 alterations and furthers our understanding of how ER+ breast cancer gives rise to lethal metastatic disease." (PMID 30525098, 2018). "For muscle-invasive disease, the direct comparison of the breast cancer subtypes and bladder cancer subtypes has been shown and the four targeted genes ESR1, PGR, ERBB2 and MKI67 have been shown to be of diverse expression in bladder cancer." (PMID 28978063, 2017). "ESR1 is one of the well-established master transcriptional regulators in the breast and is epigenetically silenced in breast cancer." (PMID 29383109, 2017). "These miRNAs, hsa-miR-448 and hsa-miR-124-3, as well as hsa-miR-661, were predicted again by the MBS in TCGA data with breast cancer molecular subtypes (bottom section) and composed interaction models with ESR1." (PMID 28793339, 2017). "The gene expression-based classification of UM shows two very robust classes similar to what has been observed for breast cancer where the expression of the estrogen receptor α (ESR1) gene defines two classes with clearly distinguished GEPs." (PMID 28229253, 2017). "ESR1 also participates in pathological processes, such as breast cancer, endometrial cancer, and osteoporosis." (PMID 28143579, 2017). "This phenomenon was also independently observed in an ESR1-positive human breast cancer cell line where microarray data comparing control and ESR1 siRNA transfected MCF7 cells showed that knockdown of ESR1 significantly increased DAB2 expression." (PMID 29196616, 2017). "The affected genes included those known to be important in breast cancer, such as ESR1 or beta-estradiol responsive genes." (PMID 29383109, 2017). "ESR1 transcriptional regulation of FGD3 mRNA expression in the breast cancer cell line ZR-75-1 was confirmed." (PMID 32913979, 2017). "The response to hormone stimulus and the response to lipids include Lox and MAOB together with ESR1, suggestive of the presence of common activator of estrogen positive type of breast cancer." (PMID 29261141, 2017). "Estrogen receptor is the specific target for endocrine therapy, and ESR1 mutations can be selected by prior aromatase inhibitor therapy in advanced breast cancer, influencing the sensitivity of standard endocrine therapies." (PMID 29088906, 2017).
breast cancer (continued). "Estradiol is a major regulator of growth for the subset of breast cancers that express the estrogen receptor (ER, ESR1)." (PMID 28924522, 2017). "Expression of ESR1, PGR, HER2 and Ki67 is important for risk stratification and therapy in breast cancer." (PMID 28978063, 2017). "One example is Patient #23 who was clinically diagnosed with HR+ breast cancer and positive for ESR1 gene expression at BL." (PMID 28489591, 2017). "An exploration of the web-based genetic analysis in the present study showed that approximately 10% of breast cancers were altered in ESR1, AR, or FOXA1 genes and generally changes in genes concurrently occurred even though the frequency was low." (PMID 29137314, 2017). "Published ESR1 chromatin immunoprecipitation sequencing data in breast cancer cell lines MCF-727 and ZR-75-128 identified a conserved ESR1 binding site within the gene locus of FGD3." (PMID 32913979, 2017). "The LogicTRN analysis provides evidence that GATA3 and ESR1 are key regulators in E2-induced cell proliferation of breast cancer cells." (PMID 29051499, 2017). "Its reported expression and homology with breast cancer pharmacological target ERα (ESR1) raised hopes for improved endocrine therapies." (PMID 28643774, 2017). "In breast cancer, certain bioinformatics methods have tried to define interactions among ESR1, co-TFs, and genes." (PMID 29051499, 2017). "Only one SNP, rs9383951, which was associated with breast cancer, was mapped to a KEGG pathway through ESR1." (PMID 28445522, 2017). "MSI-2 was found to promote breast cancer progression through binding to estrogen receptor 1 mRNA and inducing its expression." (PMID 29073938, 2017). "Taken together, these results suggest that Slug transcriptionally inhibits ERα expression by recruiting LSD1 to the ESR1 promoter in breast cancers." (PMID 28481366, 2017). "First, we evaluated the expression of key breast cancer markers: ESR1 gene was found significantly downregulated in the poor outcome group after tamoxifen therapy (t test P = 0.009; fold change = 0.67)." (PMID 28522855, 2017). "The FGD3 cell line experiment in this study and studies by others suggests that FGD3 mRNA expression is partially regulated by ESR1, an important treatment target in breast cancer, which requires further study." (PMID 32913979, 2017). "Previous study has been shown that MTA1 is negatively related to ERα expression and its recruitment to the ERpro315 region of the ESR1 promoter contributes to the epigenetic repression of ERα expression in ERα− breast cancer cells." (PMID 28415616, 2017). "We previously used a VSE-based approach to identify the enrichment of Breast Cancer (BCa) genetic predispositions at enhancers bound by FOXA1 and ESR1 in breast cancer cells." (PMID 28239419, 2017). "Estrogen receptor, a protein encoded by the ESR1 gene, is expressed in approximately 70% of breast cancers." (PMID 28361033, 2017). "GAs relevant to relapsed/metastatic breast cancer management were identified, including diverse ESR1 GAs." (PMID 28945887, 2017). "The E380Q ESR1 mutation was found in 16% (2/12) and the other ESR1 LBD mutations were five (41.6%) of Y537S, and four each (33.3%) of D538G, Y537N, and Y537C, in 12 ESR1 mutant breast cancer patients." (PMID 29166868, 2017). "Three of the four patients with BL samples that expressed ESR1 before start of therapy had clinically diagnosed HR+ breast cancer but in one patient (#8) the disease had changed phenotype from primary tumor (HR+) to metastasis (TNBC)." (PMID 28489591, 2017).